MAT2B (methionine adenosyltransferase 2 non-catalytic beta subunit)
Diseases named in the same sentence as MAT2B in open-access papers:
MAT2B is named in the same sentence as 34 diseases in open-access papers, as found by Europe PMC text mining. Sharing a sentence is not in itself a finding about the gene and the disease. The quoted sentences say what the papers report.
hepatocellular carcinoma (11 papers, 2011 to 2022). A malignant tumor that arises from hepatocytes. "Another study showed that circular RNA MAT2B was reported to promote glycolysis and malignancy of hepatocellular carcinoma through the miR-338-3p/PKM2 axis under hypoxic stress." (PMID 34489401, 2021). "The conversion of key enzymes of methionine metabolism methionine adenosyltransferase (MAT) 1 A and MAT2A/MAT2B is closely related to fibrosis and hepatocellular carcinoma." (PMID 33273451, 2020). "Of note, a novel circRNA, circ-MAT2B, has recently been reported as a key promoter of hepatocellular carcinoma malignancy." (PMID 32467667, 2020). "Consistent with previous studies, our results showed that miR-21-3p directly reduced the expression of both MAT2A and MAT2B resulting in increasing intracellular SAM contents that have been proven to impair the growth of hepatoma cells." (PMID 24098708, 2013). "Because MAT2A and MAT2B play vital role in facilitating the growth of hepatoma cells, they are valid targets for antineoplastic therapy." (PMID 24098708, 2013). "For instance, circRNA MAT2B sponged miR-338-3p to promote glycolysis and malignancy in hepatocellular carcinoma (HCC), while circPAN3 mediated drug resistance in acute myeloid leukemia through binding with miR-153-5p/miR-183-5p." (PMID 35840998, 2022). "For example, in hepatoma cells, TNF-induced activation of MAT2B further promoted tumor growth via NF-κB pathway." (PMID 31686458, 2019). "Increased expression of MAT2B also provides a growth advantage to hepatoma cells, and although it is not expressed in normal liver, its expression is increased in liver cirrhosis and HCC." (PMID 24212770, 2011).
liver cancer (9 papers, 2010 to 2025). An epithelial or non-epithelial malignant neoplasm that arises from the liver. "In order to delineate targets of MAT2B in liver cancer cells, our laboratory employed a proteomics approach to identify novel binding partners for MAT2B variants." (PMID 24212770, 2011). "Based on these findings and previous reports, we opted to validate the role of MAT2B/m6A modification in liver cancer." (PMID 39353892, 2024). "Studies on the use of specific RNAi against MAT2A or MAT2B genes are limited to in vitro analysis in human liver cancer cell lines." (PMID 24212770, 2011). "Leptin has a mitogenic potential in liver cancer cells, which is mediated through the induction of Mat2a and Mat2b genes." (PMID 20808936, 2010). "Interestingly, MAT2B exists in two isoforms, V1 and V2, and MAT2B V1 acts as a NF-κB-dependent survival factor in liver cancer cells." (PMID 39941901, 2025). "Moreover, the expression of the regulatory subunit MAT2B is frequently linked to the increase in MAT2A, conferring growth advantage to liver cancer cells and potentially serving as biomarkers." (PMID 39941901, 2025). "Moreover, MAT2B is critical for the tumorigenesis of liver cancer and KD repressed the tumor formation through, at least partially, the MAT2B-MAT2A interaction." (PMID 39353892, 2024). "One of these protective genes in liver cancer cells is MAT2B V1." (PMID 24212770, 2011). "Hence, MAT2B V1 acts as a NF-κB-dependent survival factor in liver cancer cells." (PMID 24212770, 2011). "MiR-203 transfection in HepG2 and Huh7 liver cancer cells targeted the 3’-UTR of MAT2A and MAT2B, inhibiting MAT2A and MAT2B mRNA levels and MATα2 and MATβ2 protein expression." (PMID 31073374, 2019). "MiR-203 transfection of HepG2 and Huh7 liver cancer cells targets the 3′-UTR of MAT2A and MAT2B and strongly inhibits the expression of MAT2A and MAT2B mRNAs and MATα2 and MATβ2 proteins." (PMID 31234428, 2019). "Previous studies have found that MAT2B and GIT1 interact and are overexpressed in most human liver cancer and colon cancer specimens." (PMID 30379973, 2018). "In the HepG2 liver cancer cell line, TNF-α upregulates MAT2B mRNA through AP-1 and NF-κβ pathways." (PMID 39353892, 2024).
breast carcinoma (5 papers, 2017 to 2025). "Direct inhibition of MAT2B suppressed cell growth and migration and induced apoptosis in breast cancer cell MDA-MB-231 and MDA-MB-468." (PMID 34065390, 2021). "Also, MAT2B expression level positively correlates with cell growth and migration capacity of breast cancer cell lines and with the poor prognosis of human breast cancers." (PMID 39941901, 2025). "Methionine Adenosyltransferase 2B (MAT2B) has been determined to be involved in cell metabolism including proliferation and apoptosis; further, higher expression of MAT2B was correlated with good prognosis in estrogen receptor-positive breast cancer patients." (PMID 33807872, 2021). "Increased MAT2A and MAT2B expression occurs in human liver and colon cancers and increased MAT2A expression has also been reported in human gastric cancer and tamoxifen-resistant breast cancer cells." (PMID 29108270, 2017).
colon cancer (4 papers, 2015 to 2018). "MAT2A expression is linked to increased growth and cancer cell survival, while high MAT2B expression is linked to increased activity of RAS-RAF-MEK-ERK in colon cancer cells." (PMID 29108270, 2017). "Although MAT2A and MAT2B expression are induced in parallel in liver and colon cancers, the underlying mechanism that may connect them has remained unclear." (PMID 29108270, 2017). "For example, it has been shown that methionine adenosyltransferase 2B (MAT2B) and GIT1 form a complex to control cancer cell growth and are overexpressed in most human liver and colon cancer specimens." (PMID 26462147, 2015).
prostate carcinoma (3 papers, 2017 to 2018). A carcinoma that arises from epithelial cells of the prostate gland. "The increased expression of MAT2B happens in human liver, colon, gastric, breast, pancreas and prostate cancer." (PMID 30379973, 2018). "INMT was previously identified as predicting disease progression risk in prostate cancer whereas MAT2B has not previously been implicated in prostate cancer risk or etiology." (PMID 28216563, 2017). "Like CRC, MAT2A and MAT2B expression is induced in human pancreas and prostate cancers." (PMID 29108270, 2017).
COVID-19 (2 papers, 2022). A disease caused by infection with severe acute respiratory syndrome coronavirus 2. "On the other hand, higher methylation of PSMB9, MRPS2, MFHAS1, and MAT2B genes are known to be expressed in COVID-19 patients with high viral load or severe infection, which could translate to a lower expression of those genes." (PMID 36371196, 2022).
Anxiety (1 paper, 2025). Intense feelings of nervousness, tension, or panic often arise in response to interpersonal stresses. "MAT2B is linked to anxiety behaviors through genetic variations impacting responses in animal models." (PMID 40125487, 2025). "Overall, while some genes, like MAT2B, show potential ties to anxiety, many require further exploration to understand the polygenic nature of anxiety disorders." (PMID 40125487, 2025). "Recent GWAS have also identified seven significant genetic loci—RNU6–168P, MAT2B, DKK2, DIP2C, COL22A1, OR4L1, and ATXN1—that influence anxiety traits in Caesarean-born offspring." (PMID 40125487, 2025).
Bladder Urothelial Carcinoma (1 paper, 2022). "A comparison with the cancer genome atlas TCGA reveals a downregulation of SIRT1 and MAT2B for several urogenital cancer entities like, Bladder Urothelial Carcinoma, Kidney renal papillary cell carcinoma, Kidney Chromophobe, Pan-kidney cohort (KICH+KIRC+KIRP)." (PMID 36170022, 2022).
brain cancer (1 paper, 2016). A primary or metastatic malignant neoplasm affecting the brain. "Notably, in the presence of the nearly 200 other variables in the computations, the met cycle—especially MAT2B—still contributed substantially to DNA methylation prediction (MAT2B was ranked among the top 5% of highly selected variables in prostate, breast, liver, lung and brain cancers)." (PMID 27966532, 2016).
colorectal cancer (1 paper, 2021). A primary or metastatic malignant neoplasm that affects the colon or rectum. "The expression of MAT2A and MAT2B is induced in HCC and colorectal cancers (CRC)." (PMID 34209866, 2021).
depression (1 paper, 2020). "In the bivariate meta-analyses of the broad depression phenotype and self-reported MDD, three loci (NEGR1, MAT2B, MUC21) reached genome-wide significance and all were replicated." (PMID 30626913, 2020).
hepatitis C virus infection (1 paper, 2020). A viral infection caused by the hepatitis C virus. "Methionine adenosyltransferase 2B (MAT2B) and acireductone dioxygenase 1 (ADI1), which regulate HCC development and hepatitis C virus infection, respectively, were among the top 10 HCCPMs predicted by dBMHCC." (PMID 32497121, 2020).
intrahepatic cholangiocarcinoma (1 paper, 2025). A carcinoma that arises from the intrahepatic bile duct epithelium in any site of the intrahepatic biliary tree. "Univariate logit binomial analysis, with the outcome being the proliferative subclass status of intrahepatic cholangiocarcinoma, confirmed the significance of the probes for seven enzymes: FH, MAT2B, PLOD2, PLOD1, PDE6D, ALDOC, and NT5DC3." (PMID 40034261, 2025). "Based on the training and validation cohorts of intrahepatic cholangiocarcinoma (ICA) bulk transcriptomes, seven metabolic enzymes were confirmed to be overexpressed in cases with poor prognosis: FH, MAT2B, PLOD2, PLOD1, PDE6D, ALDOC, and NT5DC3." (PMID 40034261, 2025).
liver diseases (1 paper, 2025). "A shift from MAT1A to MAT2A/MAT2B is observed in multiple liver diseases, indicating its involvement in liver growth and dedifferentiation." (PMID 40034261, 2025).
melanoma (1 paper, 2018). A malignant, usually aggressive tumor composed of atypical, neoplastic melanocytes. "MAT2B is crucial in the proliferation and tumorigenicity of melanoma cells." (PMID 30379973, 2018).
pancreas cancers (1 paper, 2017). "Indeed, both SAMe and MTA treatment lowered the expression of MAT2A and MAT2B, which increased migration of prostate and pancreatic cancer cells when overexpressed." (PMID 29108270, 2017).
cancer (17 papers, 2013 to 2025). A tumor composed of atypical neoplastic, often pleomorphic cells that invade other tissues. "Overexpression of MAT2B variants resulted in higher cytoplasmic human antigen R content and in a higher expression of its target genes, such as cyclin D1 and cyclin A, thus promoting cancer growth and progression." (PMID 34209866, 2021). "Our results illustrate that higher levels of MAT2B are associated with more ‘regulated' methylation and higher survival, suggesting potentials for genetic or dietary interventions with methionine cycle intermediates in cancer patients." (PMID 27966532, 2016). "Indeed, both MAT2B splicing variants offer the cancer cell a growth advantage." (PMID 34209866, 2021). "As an enzyme related to methionine metabolism, MAT2B can act as a cancer suppressor gene in BC development." (PMID 38239641, 2023). "MAT2B can induce the growth and survival of cancer cells, enhance tumor migration and play a carcinogenic role." (PMID 30379973, 2018). "Taken together, MAT2A and MAT2B are important targets of miR-34a/b and SAMe and MTA target this axis, suppressing MAT2A/MAT2B while raising miR-34a/b expression, inhibiting cancer metastasis." (PMID 29108270, 2017). "MAT2A and MAT2B proteins are induced in multiple cancers in parallel because they stabilize each other." (PMID 29108270, 2017). "Here we confirmed that the two MAT proteins stabilize each other using knockdown of endogenous MAT2A and MAT2B in multiple human cancer cell lines." (PMID 29108270, 2017). "Application of the integrative modelling to cancer genes revealed a major role for MAT enzymes (MAT2B and MAT2A), as well as PHGDH and GATM—enzymes involved in serine and glycine metabolism, respectively." (PMID 27966532, 2016). "Interestingly, SAMe and MTA promote miR-34a/b expression reducing MAT2A and MAT2B abundance and inhibiting cancer metastasis." (PMID 39941901, 2025). "Further investigationis needed to properly understand the cellular regulation of Mat2A,the cellular role of Mat2B, and the potential ramifications that thesefactors may have on cancer therapies." (PMID 34780697, 2021). "In recent years, much broader roles have been attributed to MAT2B in cancer biology." (PMID 34209866, 2021). "Our findings provide evidence showing the essential biological relevance of circRNA in cancer, and uncover that deregulation of circ-MAT2B may be responsible for GC malignant progression." (PMID 32467667, 2020). "As in the case of local methylation, cancer gene methylation was also more strongly explained by the expression of MAT2B compared with other met cycle variables on average (selected by 24% of all integrative models), consistent with the function of this enzyme that directly affects SAM levels." (PMID 27966532, 2016). "The underlying mechanisms for MAT2A/MAT2B parallel induction in these cancers are not clear." (PMID 29108270, 2017). "MAT2B, a key regulator of methionine metabolism, can be inhibited by cycloleucine or FIDAS-5 to interfere with methylation processes in cancer cells." (PMID 40034261, 2025). "MAT2B and GIT1 are frequently overexpressed in human liver and colon cancers, constituting a mechanism of growth and metastasis in these types of cancers." (PMID 39941901, 2025). "In summary, we have identified MAT2A and MAT2B as direct and indirect targets of miR-34a and miR-34b, and that the two MAT proteins are important mediators of the effect of miR-34a/b on cancer cell growth, migration and invasion." (PMID 29108270, 2017). "The switch is accompanied with an increasing expression of MAT2B, which results in decreased SAM levels and facilitates cancer cell growth." (PMID 24098708, 2013). "The increased expression of MAT2A and MAT2B in HCC results in decreasing SAM levels and facilitates cancer cell growth." (PMID 24098708, 2013). "The MAT1A:MAT2A switch, which was accompanied with an increasing expression of MAT2B, results in decreasing SAM levels and facilitates cancer cell growth." (PMID 24098708, 2013).
cancer (continued). "The recent observation that the inhibition of MAT2A and MAT2B expression by miRNAs leads to a rise of endogenous SAM and strong inhibition of cancer cell growth could open new perspectives to the treatment of HCC." (PMID 31234428, 2019). "The aims of the current work were to examine whether miR-34 family members regulate MAT2A and MAT2B expression and whether SAMe and MTA target this axis in multiple human cancers where miR-34a has been reported to be down-regulated." (PMID 29108270, 2017). "In addition, increased MAT2B expression in HCC also results in decreased SAM levels and facilitates cancer cell growth." (PMID 24098708, 2013). "We may not be able to perform Mat2b knockout and m6A sequencing for every type of cancer, but we have examined the relationship between Mat2b expression and m6A levels in various cancer types." (PMID 39353892, 2024). "Induction of MAT2A/MAT2B confers growth and survival advantage to cancerous cells and enhancing tumor migration; hence, understanding the role of MAT genes in tumorigenesis can help develop potential and effective strategies for cancer treatment and chemoprevention." (PMID 34065390, 2021). "However, if it enhances MAT2B expression, then it could activate MEK/ERK to drive cancer cell migration." (PMID 29108270, 2017). "Unlike MAT2A and MAT2B, which are strongly related to HCC, EEF2K is increased in many cancers, including HCC, allowing tumor growth and resisting cell death." (PMID 24098708, 2013).
tumor (12 papers, 2013 to 2025). "While over-expression of Myc and Ctnnb1 promoted tumorigenesis in mouse liver, knockdown of Mat2b largely repressed tumor formation." (PMID 39353892, 2024). "The findings indicated that the tumor suppressor activity of miR-203 is mediated by MAT2A and MAT2B downregulation and highlighted an oncogenic activity of MAT2B, linked to AKT activation." (PMID 34209866, 2021). "In human colorectal cancer cell lines, inhibition of MAT2A and MAT2B by SAM or miR-34a/b expression inhibited tumor migration and invasion in vitro." (PMID 34065390, 2021). "Stable knockdown of circ-MAT2B dramatically inhibited GC cell viability, colony formation, DNA synthesis, glucose uptake and lactate production in vitro, and retarded tumor growth in vivo." (PMID 32467667, 2020). "The xenograft tumor model confirms that the Circ-MAT2B gene inhibits tumor growth in vivo." (PMID 39816354, 2024). "Induction of MAT2A/MAT2B favors tumor growth and survival and also enhances tumor migration." (PMID 34065390, 2021). "The results showed that knockdown of circ-MAT2B remarkably reduced tumor volume and weight." (PMID 32467667, 2020). "The in vivo role of circ-MAT2B was evaluated by using xenograft tumor model." (PMID 32467667, 2020). "Lastly, we established xenograft tumor model to test whether circ-MAT2B also functioned in vivo." (PMID 32467667, 2020). "In HCC, miR-203 expression levels were inversely correlated with tumor cell proliferation, aggressiveness markers, and extent of MAT2A and MAT2B expression." (PMID 34209866, 2021). "The tumor suppressor activity of miR-203 in HCC was proposed to be partially dependent on its inhibition of MAT2A and MAT2B." (PMID 34065390, 2021). "Overall, our results demonstrate that miR-21-3p functions as a tumor suppressor by directly targeting both MAT2A and MAT2B, indicating its therapeutic potential in HCC." (PMID 24098708, 2013). "Subsequently, we performed quantitative reverse-transcription polymerase chain reaction (qRT-PCR) to examine the expression levels of the seven key prognostic genes—CEBPB, TANK, MAT2B, TMEM165, CCDC167, CYFIP1, and COX17—in the CEBPB+CAF prognostic model in the tumor tissues." (PMID 40145099, 2025). "In conclusion, our results demonstrate, for the first time, that the tumor suppressor miR-203 targets the 3’-UTRs of MAT2A and MAT2B and inhibits their expression, and show that miR-203 expression is genetically regulated and strongly contributes to determine patients’ outcome." (PMID 31073374, 2019). "As for MAT2B, it has been demonstrated to inhibit cell growth, colony formation and induction of apoptosis of A375 and mel-rm cell lines in vitro, affect the expression of BCL2 and XAF1 proteins, and prolong the growth of transplanted tumor in vivo." (PMID 30379973, 2018).
infection (2 papers, 2021 to 2022). The state of being infected such as from the introduction of a foreign agent such as serum, vaccine, antigenic substance or organism. "During infection, the viral protein Nsp9 is seen to react with MAT2B." (PMID 34353886, 2021).
metabolic disorder (1 paper, 2013). "Mammals encode a liver-specific isoenzyme, MAT1A, that is genetically linked with an inborn metabolic disorder of hypermethioninaemia, as well as a ubiquitously expressed isoenzyme, MAT2A, whose enzymatic activity is regulated by an associated subunit MAT2B." (PMID 23425511, 2013).
MAT2B also shares sentences with these, for which no sentence is quoted: gastric cancer (3 papers); anxiety disorder (1); atherosclerosis (1); brain injuries (1); ischemic stroke (1); liver cirrhosis (1); neuroblastoma (1); pancreatic cancer (1); renal carcinoma (1); schizophrenia (1); Sepsis (1); steatosis (1); urogenital cancer (1); Wilson disease (1).